NAAA (N-acylethanolamine acid amidase)
Description:
Degrades bioactive fatty acid amides to their corresponding acids, with the following preference: N-palmitoylethanolamine > N-myristoylethanolamine > N-lauroylethanolamine = N-stearoylethanolamine > N-arachidonoylethanolamine > N-oleoylethanolamine. Also exhibits weak hydrolytic activity against the ceramides N-lauroylsphingosine and N-palmitoylsphingosine.
Synonyms: ASAHL; PLT
Tractability: Small molecule: a structure with a bound ligand is known; a high-quality ligand is known; it belongs to a druggable protein family. Antibody: UniProt places it where antibodies can reach, with high confidence; UniProt predicts a signal peptide or a membrane-spanning region. PROTAC: ubiquitination databases record sites on it; its protein half-life has been measured; a small molecule that binds it is known.
Target class: Enzyme; Hydrolase
Gene: Protein-coding gene on chromosome 4 (75,910,655 to 75,941,013, reverse strand). Ensembl gene ENSG00000138744.
Subcellular location: Lysosome; Membrane
Pathways (Reactome):
Neuronal System: Neurotransmitter release cycle
Gene Ontology:
Molecular function: DNA-binding transcription factor binding; fatty acid amide hydrolase activity; hydrolase activity, acting on carbon-nitrogen (but not peptide) bonds; N-(long-chain-acyl)ethanolamine deacylase activity; N-acylsphingosine amidohydrolase activity
Biological process: fatty acid metabolic process; N-acylethanolamine metabolic process; N-acylphosphatidylethanolamine metabolic process; sphingosine metabolic process
Cellular component: cytoplasm; extracellular exosome; lysosome; membrane; lysosomal lumen
Genetic constraint (gnomAD): Loss-of-function variants: 34 observed, 39.69 expected, observed/expected ratio (o/e) 0.86, 90% interval 0.65 to 1.14. The upper end of that interval is the gene's LOEUF score, 1.14, which puts it in group 4 of 6, group 1 being the genes least tolerant of losing a copy. Missense variants: 439 observed, 441.28 expected, observed/expected ratio (o/e) 0.99, 90% interval 0.92 to 1.08. Synonymous variants: 174 observed, 177.15 expected, observed/expected ratio (o/e) 0.98, 90% interval 0.87 to 1.11.
Homologues: Orthologues: chimpanzee NAAA (98% identical), macaque NAAA (95% identical), rabbit NAAA (82% identical), pig NAAA (80% identical), guinea pig NAAA (76% identical), mouse Naaa (76% identical), rat Naaa (76% identical), tropical clawed frog naaa (54% identical), Caenorhabditis elegans Y55D5A.3 (31% identical). Paralogues in human: ASAH1 (32% identical).
Diseases named in the same sentence as NAAA in open-access papers:
NAAA is named in the same sentence as 22 diseases in open-access papers, as found by Europe PMC text mining. Sharing a sentence is not in itself a finding about the gene and the disease. The quoted sentences say what the papers report.
bladder cancer (2 papers, 2020). "With the aim of better understanding the impact of the FAAH and NAAA expressions on bladder cancer development, we split patients into two groups—high and low expressors of these enzymes." (PMID 32260109, 2020). "N-acylethanolamine acid amidase (NAAA), another eCB degrading enzyme, was reported as a promising tool in cancer therapy, as NAAA inhibitors reduced bladder cancer cells proliferation and inhibited migration in vitro." (PMID 32316328, 2020). "To better understand the role of ECs and NAEs in bladder cancer, we analyzed gene expression data from TGCA database regarding the metabolic pathway of the ECS, comprising the synthetic enzymes (PLCB1-4, PTPN22, ABHD4, GDE1, DAGLA, DAGLB, and NAPE-PLD) and the hydrolytic ones (FAAH, NAAA, and MGLL)." (PMID 32260109, 2020).
breast carcinoma (2 papers, 2022). "The total levels of NAAA mRNAs in breast cancer cells were significantly higher as compared to normal breast epithelial cells MCF-10A cells." (PMID 36564457, 2022).
colon carcinoma (2 papers, 2020 to 2025). "NAAA, the main PEA hydrolytic enzyme, plays an important role in human colon cancer." (PMID 40183090, 2025).
endometritis (2 papers, 2022 to 2024). An acute or chronic, usually bacterial infectious process affecting the endometrium. "They reported that cows defined as subclinical endometritis/with endometrial inflammation exhibited increased mRNA expression of CNR2 and decreased expression of FAAH1 and NAAA, similar to our observations." (PMID 39273135, 2024).
anorexia nervosa (1 paper, 2008). A disorder most often seen in adolescent females characterized by a refusal to maintain a minimally normal body weight, an intense fear of gaining weight, a disturbance in body image, and, in postmenarcheal females, the development of amenorrhea. "The aim of this study was to analyse whether nucleotide sequence variations in the CNR1, FAAH, NAAA and MGLL genes are associated with anorexia nervosa (AN)." (PMID 19014633, 2008).
dependence (1 paper, 2020). "Numerous NAAA inhibitors have been designed and regarded as efficient pharmacological tools in the control of various pathological conditions by reducing nicotine dependence, alleviating osteoarthritis development, and attenuating inflammatory and neuropathic pain." (PMID 32326173, 2020).
glioma (1 paper, 2020). A benign or malignant brain and spinal cord tumor that arises from glial cells (astrocytes, oligodendrocytes, ependymal cells). "In rat C6 glioma cells, treatment with PEA-um (10 μM) significantly reduced iNOS and COX-2 expression following damage induced by LPS/IFN γ, but the protective effects of PEA-um were enhanced in LPS/IFN γ-stimulated cells in which NAAA enzyme was muted." (PMID 33050589, 2020).
injury (1 paper, 2020). Damage inflicted on the body as the direct or indirect result of an external force, with or without disruption of structural continuity. "Another NAAA inhibitor F215 showed anti-inflammatory effects both in LPS-induced acute lung injury model and TPA-induced local skin inflammation model." (PMID 32326173, 2020).
melanoma (1 paper, 2024). A malignant, usually aggressive tumor composed of atypical, neoplastic melanocytes. "Although the cannabinoid system has been reported to play a role in melanoma, only two articles have addressed the importance of FAAH and NAAA in melanoma progression." (PMID 38369184, 2024).
multiple sclerosis (1 paper, 2020). A progressive autoimmune disorder affecting the central nervous system resulting in demyelination. "N-acylethanolamine-hydrolyzing acid amidase (NAAA) is a lysosomal enzyme that inhibits the degradation of palmitoylethanolamide (PEA), an endogenous lipid that induces analgesic, anti-inflammation, and anti-multiple sclerosis through PPARα activation." (PMID 33117168, 2020).
Parkinsonism (1 paper, 2025). Characteristic neurologic anomaly resulting from degeneration of dopamine-generating cells in the substantia nigra, a region of the midbrain, characterized clinically by shaking, rigidity, slowness of movement and difficulty with walking and gait. "NAAA is a proinflammatory protein emerging as a promising target in mouse models of parkinsonism." (PMID 40485680, 2025).
cancer (6 papers, 2012 to 2022). A tumor composed of atypical neoplastic, often pleomorphic cells that invade other tissues. "Of note, several cancer associated genes such as CDH6, FOXM1, NAAA and CXCL10 were amplified and upregulated." (PMID 36352274, 2022). "N‐acylethanolamine‐hydrolyzing acid amidase (NAAA), an amidase acting at acidic pH,41 is reported to be highly expressed in several types of cancer cells." (PMID 34173723, 2022). "The direct involvement in cancer of enzymes involved in synthesis and degradation of the endogenous ligands has been confirmed by several studies that reported the up-regulated expression of NAAA, MAGL, and FAAH in different cancers." (PMID 31979368, 2020). "Meanwhile, we demonstrate that NAAA expression was correlated with TMB in 4 cancers and with MSI in 10 cancers." (PMID 35069601, 2021). "Other enzymes, like lysosomal hydrolase N-acylethanolamine hydrolyzing acid amidase (NAAA) that degrades AEA, OEA, and PEA, constitute potential targets in cancer." (PMID 31979368, 2020).
tumor (3 papers, 2021 to 2023). "Since NAAA knockout mice are not available, future studies in my lab are aimed to genetically validate the importance of NAAA for tumor growth and metastatic potential, by employing shRNAs to knockdown NAAA, using pLKO lentiviral vectors." (PMID 36564457, 2022). "In this study, we hypothesized that enhancement of endogenous levels of PEA, via inhibition of its catalytic enzyme NAAA, should lead to inhibition of pro-tumor signaling cascades in TNBC, resulting in reduced inflammation and tumor growth." (PMID 36564457, 2022).
NAAA also shares sentences with these, for which no sentence is quoted: colitis (3 papers); acute lung injury (1); Anxiety (1); chronic kidney disease (1); Cirrhosis (1); Neonatal respiratory distress (1); neuroblastoma (1); osteoarthritis (1); triple-negative breast carcinoma (1).